ENSG00000131152 (novel protein)
Gene: Protein-coding gene on chromosome 16 (87,302,876 to 87,334,273, reverse strand). Ensembl gene ENSG00000131152.
Genetic constraint (gnomAD): Loss-of-function variants: 24 observed, 25.7 expected, observed/expected ratio (o/e) 0.93, 90% interval 0.68 to 1.31. Missense variants: 354 observed, 330.47 expected, observed/expected ratio (o/e) 1.07, 90% interval 0.98 to 1.17. Synonymous variants: 146 observed, 141.32 expected, observed/expected ratio (o/e) 1.03, 90% interval 0.9 to 1.18.